IL2 (interleukin 2)
Diseases named in the same sentence as IL2 in open-access papers (continued):
Sharing a sentence is not in itself a finding about the gene and the disease.
type 2 diabetes (12 papers, 2006 to 2025). "The decreased regulatory function of Treg and impaired IL-2 signaling were found in patients with type 2 diabetes mellitus (T2D)." (PMID 33080827, 2020). "Both type 1 and type 2 diabetes are associated with increased blood concentrations of several inflammatory biomarkers, including C-reactive protein (CRP), interleukin (IL)-2, IL-6 and tumour necrosis factor-alpha (TNF-α)." (PMID 27544079, 2016). "C-reactive protein levels were not affected by n-3 supplementation (3 g/day for eight weeks) in a randomized control trial for persons with type 2 diabetes; yet IL-2 and TNF-α, other indicators of inflammation, were reduced in the n-3 group." (PMID 31667003, 2013). "Metformin, a prescribed drug for type 2 diabetes, has been reported to protect CD8+ tumor-infiltrating lymphocytes from apoptosis and exhaustion characterized by decreased production of IL-2, TNF-α, and interferon-γ (IFN-γ) via AMP-activated protein kinase (AMPK) activation." (PMID 34880864, 2021).
abortion (11 papers, 2017 to 2025). the ending of pregnancy by removing a fetus or embryo before it can survive outside the uterus. "When IL-2 levels are high, pregnant women have a higher susceptibility for spontaneous abortion, preterm delivery, IUGR, and the development of PE." (PMID 34685775, 2021). "Murine studies demonstrate that administration of pro-inflammatory cytokines (i.e. TNFα, IFN, IL-2) into pregnant mice causes increased abortion." (PMID 28636613, 2017). "In patients with spontaneous abortion, the 2−ΔΔCT value of IL-2 was decreased compared to healthy pregnant women, but this decrease was not statistically significant (p = 0.509)." (PMID 40141672, 2025). "In women experiencing spontaneous abortion, IL-2 and IL-17 expression levels decreased by 0.63-fold and 0.01-fold, respectively (p = 0.006007 and p = 0.001464)." (PMID 40141672, 2025). "Age, gravity, parity, abortion, smoking, presence of chronic disease and IL-2 were similar between the spontaneous abortion patients and healthy pregnant women (p > 0.05)." (PMID 40141672, 2025). "In this study, it was observed that the 2−ΔΔCT expression level of IL-2 in spontaneous abortion patients decreased compared to healthy pregnant women, but this decrease was not statistically significant." (PMID 40141672, 2025). "It was observed that the 2−ΔΔCT in the expression level of IL-2 in spontaneous abortion patients decreased compared to healthy pregnant women, but this decrease was not statistically significant (p = 0.509)." (PMID 40141672, 2025). "They found IFN-γ, TNF-α, IL-2, IL-6 and IL-17A cytokines were significantly increased in spontaneous abortion ((SA) group and recurrent miscarriage (RM) group (Ctinfected) versus controls." (PMID 35392343, 2021). "Furthermore, this study found that the expression levels of IL-2 and IL-17 were reduced by 0.63-fold and 0.01-fold, respectively, in pregnant women with spontaneous abortion." (PMID 40141672, 2025). "The decrease in IL-2 expression might suggest a reduction in protective immune responses in patients with spontaneous abortion." (PMID 40141672, 2025). "In conclusion, the fold changes in IL-2, IL-17, and IL-27 expression levels between spontaneous abortion patients and healthy pregnant women reveal possible alterations in immune regulation that might contribute to spontaneous abortion." (PMID 40141672, 2025). "The decrease in IL-2 expression might suggest a reduction in protective immune response in patients with spontaneous abortion." (PMID 40141672, 2025). "To determine whether tregitope treatment restores the Th1/Th2 balance during pregnancy in abortion-prone mice, we examined the levels of IL-2, IL-4, IL-10, IFNγ and TGFβ1 cytokines in blood sera." (PMID 32601347, 2020). "It has been reported that the VEGFA expression decreases in the endometrial tissue of patients with idiopathic recurrent abortion during the peri-implantation period, which may be related to the downregulation of angiogenic cytokines, including IL-2, IL-6, and IL-8." (PMID 40585325, 2025). "IL-2 and INF-γ, produced by Th1 cells, play important roles for the induction of implantation failure and abortion while the proinflammatory cytokine IL-17 is involved in the pathogenesis of abortion and PTB." (PMID 35721757, 2022). "In the present study, we cocultured PBMCs with their trophoblasts, and the PBMCs in the normal groups displayed an immune-tolerant trait characterized by the production of higher levels of IL-4 and lower IL-2 and IFN-γ than those in the abortion-prone group." (PMID 29651447, 2018). "This may suggest that IL-2 could play a role in the pathophysiology of spontaneous abortion, but the data obtained in this study do not strongly support this relationship." (PMID 40141672, 2025).
allergic rhinitis (11 papers, 2014 to 2025). Inflammation of the nasal mucous membranes caused by an IgE-mediated response to external allergens. "Ultimately, the ameliorative effect of dictamnine on allergic rhinitis mice was confirmed through nasal symptom score, serum pharmacodynamic indices (immunoglobulin E (IgE), histamine, IL-2, IL-4, IL-6, and TNF-α), and histopathology." (PMID 40520177, 2025). "Compared to allergic rhinitis mice, CCR3mAb2 and CCR3mAb3 groups had increased trends in Th1 cytokines (IL-2 and IFN-γ), with statistical significance; and decreased trends in Th2 cytokines (IL-4, IL-5, and IL-13)." (PMID 38212473, 2024). "In this study, increased nasal secretion of IL-2 and IL-6 was considered anti-inflammatory for allergic rhinitis." (PMID 38707001, 2024). "After different administrations, CCR3mAb i.p. group had increased trends in Th1 cytokines (IFN-γ and IL-2) compared to allergic rhinitis mice, with statistical significance; and decreased trends in Th2 cytokines (IL-4, IL-5, and IL-13)." (PMID 38212473, 2024). "Studies show that acute moderate exercise increases the IL-2/IL-4 ratio in allergic rhinitis patients, reducing inflammation, while 2 months of moderate training in healthy males significantly increased IFN-γ and IL-2 levels in PBMC cultures, enhancing Th1 responses." (PMID 40777031, 2025). "In the gradient concentration experiment, the results showed that the expression levels of Th1 cell cytokines (IL-2 and IFN-γ) in allergic rhinitis group were significantly lower than those in the blank control group and the CCR3mAb23 intraperitoneal injection group, with statistical significance." (PMID 38212473, 2024).
autism (11 papers, 2011 to 2025). Persistent deficits in social interaction and communication and interaction as well as a markedly restricted repertoire of activity and interest as well as repetitive patterns of behavior. "Autism and deviations in cognitive capacity are also characterized by disturbed IL-2 and associated to pesticide exposure." (PMID 37927185, 2023). "Animal models suggested that IL-2 was required for cell development in the mesolimbic and mesostriatal systems, whose pathology is associated with autism and cognitive disturbances." (PMID 37927185, 2023). "They found an imbalance between Th1 and Th2 cytokines with increased IL-4+CD4+ T cells and IL-4+CD8+ T cells and decreased proportions of IFN-γ+CD4+ T cells, IL-2+CD4+ T cells, and IFN-γ+CD8+ and IL-2+CD8+ T cells in children with autism." (PMID 29307081, 2018). "By contrast, elevated concentrations of IL-2, IL-4 and IL-6 were significantly associated with an increased risk of DD without autism." (PMID 21810230, 2011). "Other cytokines, IL-12, IL-2, MCP-1, MIP-1α, GM-CSF, and eotaxin, were unchanged in the plasma of subjects with autism." (PMID 36268027, 2022). "Plasma levels of IL-2 and IFN-γ havebeen reported to be increased in autism (n = 20, meanage = 10.7 years)." (PMID 21647375, 2011). "Similarly, MOD significantly reduced IL-17, IL-2, TNF-α, and NF-KB levels in the propionic acid rat model of autism‐like behavior." (PMID 40234306, 2025). "Moreover, insulin exhibited noteworthy capabilities in decreasing brain MDA, IL-2, IL-17, and TNF-α levels within autism models." (PMID 39329976, 2024). "An alternative profile of increased IL-2, IL-4 and IL-6 was more common for women who gave birth to a child subsequently diagnosed with DD without autism." (PMID 21810230, 2011). "However, our results showed elevated IL-6 and IL-2 in mothers bearing a child with DD but not autism." (PMID 21810230, 2011).
autoimmune thyroid disease (11 papers, 1990 to 2025). Inflammatory disease of the thyroid gland due to autoimmune responses leading to lymphocytic infiltration of the gland. "IL-2 deficiency has been reported in neonates, which is closely associated with abnormal regulation of tyrosine phosphorylation.One study noted that IL-2 is an identified susceptibility gene locus associated with autoimmune thyroid diseases." (PMID 41169358, 2025). "Cytotoxic T-lymphocyte associated protein 4 (CTLA-4) inhibition worsened autoimmune thyroiditis in mice via the production of interleukin (IL)-2, interferon gamma, IL-10, and IL-13 cytokines." (PMID 34234669, 2021). "Many immune-related pathways were also involved, such as the autoimmune thyroid disease, the IL2 pathway, and the intestinal immune network." (PMID 35154072, 2021). "The possibility of autoimmune thyroiditis should be anticipated in future trails combining interleukin-2 and interferon alpha-2a." (PMID 2390468, 1990). "The IL-2 targeted SPECT radiotracers, [99mTc]IL-2 and [99mTc]HYNIC-IL-2, have already been applied successfully for the visualization of vulnerable atherosclerotic plaques, transplant rejection and autoimmune thyroid disease." (PMID 35733858, 2022).
heart failure (11 papers, 2012 to 2024). Inability of the heart to pump blood at an adequate rate to meet tissue metabolic requirements. "This study also found an association of IL-2 with heart failure." (PMID 35568817, 2022). "So far, it has been found that inflammatory cytokines associated with the heart failure mechanism include TNF-α, IL-6, IL-8, IL-10, IL-1α, IL-1β, IL-2, TGF-β, and IFN-γ." (PMID 31275453, 2019). "High levels of proinflammatory cytokines, including TNF-α, IL-6, IL-1β, and IL-2, have a profound effect on pathogenesis and prognosis in heart failure." (PMID 29201273, 2017). "Moreover, we uncovered alterations in adipogenesis and oxidative phosphorylation pathways in hypertrophic cardiomyopathy and discovered a role for IL2 STAT5 signaling in heart failure." (PMID 38673810, 2024). "A recent study assessed IL-2 levels and correlated with new onset heart failure using MESA data." (PMID 35568817, 2022). "In non-diabetic patients with heart failure, metformin therapy is associated with a pronounced reduction of circulating cytokines, such as IL-2, IL-4, and C-X-C motif chemokines ligand 12 (CXCL12)." (PMID 33584319, 2021). "Second, the effects on tumor growth might not directly affect the survival of the mice due to distant metastasis or the side effects of IL-2, such as cardiac failure." (PMID 22922885, 2012). "Moreover, a recent study reports that, in a cohort of 1,213 hospitalized patients with COVID-19 and pre-existing T2D, metformin use is significantly associated with reduced heart failure and decreased circulating inflammatory markers, such as CRP, IL-6, IL-2, and TNF-α." (PMID 33584319, 2021).
migraine (11 papers, 2013 to 2025). "Utilizing the Inverse Variance Weighting (IVW) method, we uncovered a potential link between a heightened risk of migraines and diminished levels of IL-2 (OR, 0.012; 95% CI: [0.000, 0.0929]; P = 0.046)." (PMID 37938611, 2023). "Additionally, migraine may lead to decreased levels of IL-2 through a causal pathway if it is defined as an exposure in MR." (PMID 37938611, 2023). "Although there is limited research on HGF and IL-2 in migraine, our study suggests that they play a significant role in migraine pathogenesis." (PMID 37938611, 2023). "The most relevant cytokines related to migraines include IL-1, IL-2, IL-4, IL-6, IL-10, TNF-α, and TGF-β." (PMID 35896985, 2022). "In addition, Interleukin-2 (IL-2) was considered a downstream consequence of migraine (OR, 0.012; 95% CI, 0.000–0.0929; P = 0.046)." (PMID 37938611, 2023). "Therefore, it can be concluded that HGF may play a dominant role in the early onset of migraine, while IL-2 is more likely to be downstream in the disease progression." (PMID 37938611, 2023). "Studies have shown that PTGS2 participates in the pathogenesis of migraines, and the symptoms of migraine patients can be improved by inhibiting the PTGS2 proinflammatory pathway and reducing the levels of TNF-α, IL-2, and IL-6." (PMID 41009787, 2025). "Li Jinhong found that the levels of serum INF-α, IL-2, IL-17, IL-12P70, TNF-α, IL-5, IL-1β, and IL-4 were higher in adult migraine patients than in normal control group, which changed with different stages of the disease." (PMID 38356891, 2024). "For instance, some studies demonstrated an increase of proinflammatory cytokines such as IL-6, IL-2, CGRP, and TNF in migraine." (PMID 23984350, 2013). "Regarding migraine and non-disease physiological factors, the severe heterogeneity was entirely attributable to the IL-2 data point, as evidenced by the elimination of heterogeneity upon its exclusion." (PMID 40994718, 2025). "The levels of folic acid, homocysteine (Hcy), vitamin B12, interleukin-2 (IL-2), IL-4, and ferritin, and changes of NRS were compared between folic acid and conventional treatment groups stratified by different genotypes of MTHFR in migraine patients." (PMID 36619923, 2022).
neuropathy (11 papers, 2010 to 2026). A disorder affecting the nervous system that manifests with pain, tingling, numbness, and/or muscle weakness. "More common side effects associated with IL-2 therapy are dizziness, paresthesia and somnolence, followed by neuropathy and lethargy." (PMID 35454826, 2022). "Moreover, CD4 and IL-21 staining was absent in the non-neuropathic controls (NOD.WT), which suggests that the neuropathy was associated with increased IL-2–producing CD4+ T cells in peripheral nerves." (PMID 39087473, 2024). "In the context of neural inflammation, IL-2 helps to balance Th17 and Tregs, offering potential therapeutic benefits for neuropathy and autoimmune neuroinflammation by reducing inflammation." (PMID 40038202, 2025). "Severe neurotoxicity is a reported side effect of IL-2 monotherapy including neuropathy, coma, convulsions, paralysis and leukoencephalopathy." (PMID 35454826, 2022). "Previously, higher levels of systemic TNFα- and IL-2-mRNA were reported in HIV-1-negative painful neuropathies when compared with painless neuropathies." (PMID 24512313, 2014). "In addition, this recovery mechanism was also confirmed by the analyses of the inflammatory markers mainly involved in neuropathy, such as TNFα and IL-2." (PMID 36982577, 2023). "The pathogenesis of UP may involve inflammatory states, such as increased levels of pro-inflammatory cytokines (IL-6, IL-2, and TNF-α), immune changes, and neuropathy." (PMID 37675019, 2022). "Patients with painful neuropathy had a two-fold increase in IL-2 and TNF, while patients with nonpainful neuropathy had significantly higher mRNA levels of IL-4 and IL-10." (PMID 21994811, 2010). "A recent study investigated mRNA levels of proinflammatory cytokines interleukin-2 (IL-2) and tumor necrosis factor-alpha (TNF) as well as anti-inflammatory cytokines IL-4 and IL-10 among patients with painful neuropathy, nonpainful neuropathy and control participants." (PMID 21994811, 2010).
pancreatic ductal adenocarcinoma (11 papers, 2018 to 2025). An infiltrating adenocarcinoma that arises from the epithelial cells of the pancreas. "A preclinical study combining oncolytic adenovirus Ad-mTNFα-mIL2 (expressing TNF-α and IL-2) with CAR-T cells targeting mesothelin showed significant tumor attenuation in pancreatic ductal adenocarcinoma models." (PMID 40539780, 2025). "To assess the role of IL-2 in pancreatic ductal adenocarcinoma (PDAC), we compared the levels of IL-2 in tumors from 178 PDAC patients obtained from the TCGA portal with 171 normal pancreases from the GTEx portal." (PMID 38554155, 2024).
psychosis (11 papers, 2005 to 2025). "This approach highlights the importance of methodological control in inflammation research in psychosis and emphasises the potential diagnostic and research value of IL-2 as a marker of neuroimmune activation in the initial stages of the illness." (PMID 41008291, 2025). "In this context, examining the interleukins (IL-1β, IL-2, IL-6, IL-10) in these patients offers a promising path toward understanding the early immunological disturbances associated with psychosis." (PMID 41008291, 2025). "The literature supporting these findings includes studies conducted on FEDN psychosis patients, which reported elevated IL-2 concentrations and soluble IL-2 receptors (sIL-2R) as indirect markers of T-cell activation." (PMID 41008291, 2025). "It was observed that the serum levels of IL-2 and IL-6 are increased in first episode drug-naïve patients with psychosis, and that IL-3 levels are significantly increased in patients with chronic schizophrenia." (PMID 26649857, 2017). "Clinical investigations have detected increased levels of IL-2 in the CSF of schizophrenic patients manifesting symptoms of psychosis." (PMID 16000166, 2005). "This study further illuminates the immunological profile of patients experiencing a first episode of psychosis, showing that IL-1β, IL-2, and IL-10 are not only significantly altered compared to the healthy controls, but are also associated with specific dimensions of the clinical picture." (PMID 41008291, 2025). "However, psychotic symptoms (e.g., delusions or hallucinations) may develop in cancer patients with no pre-existing psychotic disorder, secondary to CTx agents such as chlorambucil, hydroxyurea, ifosfamide, asparaginase, corticosteroids, interferon-alpha, interleukin-2, and procarbazine." (PMID 39614312, 2024). "The results of the ROC analysis in our study showed that IL-2, IL-1β, and IL-10 had significant discriminatory ability in distinguishing the patients with FEDN psychosis from the healthy controls, while IL-6 did not demonstrate a statistically significant value." (PMID 41008291, 2025).
renal failure (11 papers, 2008 to 2023). "IL2 therapy is associated with multiple adverse effects including rigor, fever, capillary leak, hypotension, and renal insufficiency due to its cytokine cascade." (PMID 30342473, 2018). "While meperidine became the mainstay decades ago, there is a paucity of data regarding alternatives especially given that meperidine is renally excreted with the context of possible renal insufficiency associated with IL2 therapy." (PMID 30342473, 2018). "In the discovery of their potential to serve as drug targets, we found 10 out of 21 have been used as drug targets for drugs to treat a wide range of diseases or indications, and IL2-RA has been used as drug target for kidney failure and CKD treatment." (PMID 37407978, 2023).